CIP2A (cellular inhibitor of PP2A)
Diseases named in the same sentence as CIP2A in open-access papers (continued):
Sharing a sentence is not in itself a finding about the gene and the disease.
lung cancer (continued). "Although the mechanism of the involvement of CIP2A in lung cancer is not clearly understood, some recent studies have indicated the involvement of interleukin-10 (IL-10) in this event." (PMID 25015035, 2014). "The functions of CIP2A in lung cancer have not been fully understood yet and its clinical relevance has not yet been established." (PMID 25109354, 2014). "The expression of CIP2A is tightly restricted to embryonic stage but often re-expressed in lung cancer tissues." (PMID 25109354, 2014). "In nonsmall cell lung cancer, CIP2A elevation correlated with elevated C-Myc expression levels, and is a significant prognostic predicator for poor survival." (PMID 24307892, 2013). "More recently, a natural Chinese medicinal herbal extract of Rabdosia coetsa, rabdocoetsin B, was also shown to inhibit proliferation and induce apoptosis in a variety of lung cancer cells via CIP2A-dependent p-Akt downregulation." (PMID 22537901, 2012). "Since Akt is constitutively active in lung cancer cells and promotes cellular survival and resistance to chemotherapy and radiation, we examined the effect of CIP2A on pAkt in lung cancer." (PMID 21655278, 2011). "Taken together, CIP2A is dramatically elevated in lung cancer tumor samples compared to paired normal lung tissues." (PMID 21655278, 2011). "CIP2A is critical for lung cancer cell growth, since CIP2A knockdown by specific siRNA results in significant inhibition of cell proliferation and transformation in vitro and in vivo." (PMID 21655278, 2011). "The data demonstrated that CIP2A overexpression in lung cancer was significantly correlated with histologic type of squamous cell carcinoma (p = 0.003) and male gender (p = 0.008) that were shown to strongly link with cigarette smoking." (PMID 21655278, 2011). "Data from previous experiments showed the roles of RING1 and CIP2A in lung cancer development." (PMID 41362702, 2025). "In summary, our findings underscore CIP2A’s multifaceted role in lung cancer progression." (PMID 40943297, 2025). "CIP2A overexpression is observed in various subtypes of lung cancer, including NSCLC and SCLC." (PMID 41155727, 2025). "Moreover, we discovered that the E3 ubiquitin ligase, RING1, plays an important role in regulating the protein stability of CIP2A in lung cancer formation." (PMID 41362702, 2025). "RING1 was hypothesized to potentially influence lung cancer progression through the regulation of CIP2A protein levels." (PMID 41362702, 2025). "Therefore, the aim of our study was to investigate the prognostic value of CIP2A in lung cancer and to develop a prognostic model based on its expression." (PMID 40943297, 2025). "Knocking down CIP2A in lung cancer cells reduced cell proliferation and migration." (PMID 41362702, 2025). "MiR-383-5p exerts anti-proliferative effects on lung cancer cells by targeting CIP2A." (PMID 36313570, 2022). "An analysis of cell lines of the Genomics of Drug Sensitivity in Cancer database, however, revealed a significant correlation of CIP2A expression levels and the gefitinib and erlotinib sensitivity, which was significant for gefitinib when the analysis was restricted to lung cancer cell lines." (PMID 33804833, 2021). "In addition, EA potentiated the inhibitory effects of the natural compound celastrol on lung cancer cells in vitro and in vivo by enhancing autophagy and down‐regulating CIP2A." (PMID 30353639, 2019). "Moreover, the mechanistic studies showed that EA induces autophagy by targeting CIP2A in lung cancer cells." (PMID 30353639, 2019). "Additionally, subgroup analysis suggested that the trend of a poor overall survival with an increased CIP2A expression was present in East-Asian and European patients, as well as in lung cancer and colorectal cancer." (PMID 30044786, 2018). "To assess whether CIP2A could affect lung cancer cell growth, we either depleted CIP2A or increased CIP2A by ectopic expression of the recombinant CIP2A." (PMID 26560124, 2015).
lung cancer (continued). "But the role of CIP2A in lung cancer progression is still not well understood." (PMID 26560124, 2015). "Immunohistochemistry of the lung cancer tissue sections showed that the expression of CIP2A was frequently observed in the clinical tumor samples from the NSCLC patients and that the expression of CIP2A in the tumor samples was correlated with the expressions of p-AKT and Elk-1." (PMID 25537503, 2015). "The expression level of CIP2A in lung cancer tissues was examined by immunohistochemistry." (PMID 26560124, 2015). "And the overexpressed CIP2A in lung cancer could enhance JNK signaling through the phosphorylation of MKK4/MKK7-JNK-c-Jun pathway." (PMID 26560124, 2015). "Expression data for CIP2A in lung cancer also supported the working hypothesis that auto-antibody production in cancer may be directly linked to aberrant expression of proteins involved in tumorigenesis pathways." (PMID 25015035, 2014). "Inhibition of CIP2A by celastrol inhibited the growth of lung cancer cells in vitro and in vivo." (PMID 25015035, 2014). "Previous studies have suggested potential mechanisms to explain the erlotinib activities in EGFR-wt lung cancers, such as EGFR copy numbers, mutations in other exons of the EGFR gene, cancerous inhibitor of protein phosphatase 2A (CIP2A) pathway and VeriStrat status." (PMID 25215536, 2014). "Previous studies have shown that the overexpression of CIP2A is detected in various types of tumors, from solid tumors to hematological malignancies, including breast, gastric, head and neck, lung cancer and leukemia, and subsequently it was known as an oncofetal protein." (PMID 25109354, 2014). "We proposed that CIP2A may be a potential biomarker to be incorporated into existing biomarker arrays for lung cancer diagnosis." (PMID 25109354, 2014). "Interestingly, we identify a natural compound rabdocoetsin B, can down-regulate CIP2A protein in lung cancer cells (A through C) by inhibiting its expression at mRNA level." (PMID 21655278, 2011). "Silencing CIP2A by siRNA inhibited the proliferation and clonogenic activity of lung cancer cells." (PMID 21655278, 2011). "We studied the expression of CIP2A in lung cancer and screened for lead compounds that could target CIP2A." (PMID 21655278, 2011). "Together, these data indicate that CIP2A is essential to lung cancer proliferation and tumorigenesis, and could be an effective therapeutic target." (PMID 21655278, 2011). "Our findings strongly indicate that CIP2A could be an effective target for lung cancer drug development, and the therapeutic potentials of CIP2A-targeting agents warrant further investigation." (PMID 21655278, 2011). "Here we show that CIP2A is markedly upregulated in lung cancer tumors compared to patient-matched adjacent normal lung tissues, and report that a natural compound which triggers downregulation of CIP2A exhibits significant antitumor activity in NSCLC cell lines." (PMID 21655278, 2011). "In lung cancer, a correlation is detectable between CIP2A and c-Myc mRNA expression levels." (PMID 21610708, 2011). "Therefore, it is possible that CIP2A may regulate lung cancer progression in a JNK signaling-dependent manner." (PMID 26560124, 2015). "Therefore, CIP2A regulates AKT phosphorylation in lung cancer cells." (PMID 25109354, 2014). "Intriguingly, we found a natural compound, rabdocoetsin B which is extracted from a Traditional Chinese Medicinal herb Rabdosia coetsa, could induce down-regulation of CIP2A and inactivation of Akt pathway, and inhibit proliferation and induce apoptosis in a variety of lung cancer cells." (PMID 21655278, 2011). "In conclusion, this study highlights the critical roles of CIP2A, RING1, and DNMT1 in the development and progression of lung cancer." (PMID 41362702, 2025). "By summarizing the current understanding of the molecular mechanisms of lung cancer development and progression, we aim to propose CIP2A and RING1 as novel therapeutic targets for treating lung cancer." (PMID 41362702, 2025).
lung cancer (continued). "Erlotinib transcriptionally downregulates CIP2A to upregulate PP2A and is primarily used to treat EGFR-mutant lung cancer." (PMID 40487848, 2025). "CIP2A expression was regulated by RING1 and its activity affected the oncogenic capacity of lung cancer cells." (PMID 41362702, 2025). "CIP2A exerted oncogenic effects by inducing c-Myc, JNK, and AKT-related signaling pathways in lung cancer." (PMID 36313570, 2022). "However, whether CIP2A can be a new drug target for lung cancer is largely unclear." (PMID 21655278, 2011). "Additionally, combining PP2A activators or CIP2A inhibitors with kinase inhibitors (e.g., MEK inhibitors) or chemotherapy enhances anticancer effects, particularly in aggressive cancers like lung cancer." (PMID 41155727, 2025). "Oridonin suppresses the CIP2A/AKT and EGFR/ERK pathways in gefitinib-resistant lung cancer." (PMID 40943297, 2025). "Despite these findings, no prior studies have systematically evaluated CIP2A as a prognostic biomarker or incorporated it into a predictive model for lung cancer outcomes." (PMID 40943297, 2025). "A negative relationship was found between miR-383-5p and CIP2A expression levels in lung cancer cells and tissues." (PMID 36313570, 2022). "The increased expression of cancerous inhibitor of PP2A(CIP2A) has been described in many kinds of malignancy like HCC, breast cancer, colorectal cancer, ovarian cancer, cervical cancer, prostate cancer, lung cancer, chronic myeloid leukemia, and acute myeloid leukemia." (PMID 24307892, 2013). "Peng showed that in American-based patients, CIP2A is increased in 61 of the 72 (84.7%) lung cancer tissue specimens, which is significantly higher than in normal lung tissues (14.3%, 9/63)." (PMID 21655278, 2011). "Although direct evidence linking CIP2A modulation to changes in CD31 and p-AMPK in lung cancer is limited, the cumulative data on AKT activation, E-cadherin regulation, and tumor progression support the hypothesis that CIP2A promotes angiogenesis and suppresses metabolic regulation." (PMID 40943297, 2025). "In addition, CIP2A is overexpressed in NSCLC and correlated with a poor prognosis, and the downregulation of CIP2A and inactivation of the AKT pathway has been reported to inhibit proliferation and induce apoptosis in a variety of lung cancer cells." (PMID 25537503, 2015). "CIP2A specific siRNA was employed to evaluate its roles in lung cancer pathogenesis, and the results showed that as compared to negative control (NC), CIP2A silencing led to inhibition of clonogenic activity of A549 cells, detected by foci formation and soft agar colony formation assays." (PMID 21655278, 2011). "Therefore, further investigation into the role of DUB proteins in relation to CIP2A could provide deeper insights into the function of CIP2A in the pathogenesis of lung cancer and identifying DUB could significantly contribute to the development of CIP2A inhibitors as a therapeutic target in cancer." (PMID 41362702, 2025). "In the 60 lung cancer patients examined in this study, 28 of 36 (77.8%) smoker patients show increased expression of CIP2A in the tumor samples compared to their adjacent normal specimens, whereas 10 of 24 (41.7%) nonsmoker cases exhibit up-regulated CIP2A at protein level (p = 0.004)." (PMID 21655278, 2011).
prostate carcinoma (23 papers, 2010 to 2025). A carcinoma that arises from epithelial cells of the prostate gland. "Patients with both HOXB13 T and CIP2A T alleles have a higher risk of prostate cancer and invasive disease, earlier biochemical recurrence, and lower disease-specific life expectancy." (PMID 36911405, 2023). "Dual carriers of HOXB13 rs138213197 T and CIP2A rs2278911 T, both of which are prostate cancer susceptibility variants, show the risk of prostate cancer with threefold higher odds than the HOXB13 T allele alone." (PMID 37097392, 2023). "The G84E variant showed a strong interaction with a CIP2A polymorphism in dual carriers; the OR for prostate cancer was 21.1 and the interaction was replicated in another Finnish cohort and with a lower risk in a Swedish population (OR 6.4)." (PMID 36882784, 2023). "This suggests that the possible interaction of HOXB13 and CIP2A is related to prostate cancer susceptibility." (PMID 37097392, 2023). "CIP2A protein expression is also associated with poorly differentiated and high-risk prostate cancer." (PMID 23342256, 2012). "Expression of the CIP2A protein is increased in prostate cancer specimens and its expression is associated with poorly differentiated and high-risk tumors." (PMID 20964854, 2010). "We further evaluated the association between CIP2A staining and pre-treatment clinical prostate cancer risk group stratification based on PSA values, Gleason scores and clinical tumor staging among patients treated by radical prostatectomy (n = 31)." (PMID 20964854, 2010). "In addition, we demonstrated a positive association between prostate cancer preoperative risk stratification and CIP2A expression, further supporting the potential prognostic significance of CIP2A in prostate cancer." (PMID 20964854, 2010). "Taken altogether, CIP2A staining intensity increased significantly with increasing Gleason score, increasing pre-treatment clinical risk group stratification and increasing pathological T-class after radical prostatectomy, which are all associated with aggressive behavior of prostate cancer." (PMID 20964854, 2010). "Immunohistochemical staining revealed that CIP2A, SET, and pPP2A were found in a high-risk subgroup of prostate cancer patients and were associated with metastatic potential." (PMID 37097392, 2023). "LRRC59 has been shown to be a binding transporter of the cellular inhibitor PP2A (CIP2A) in prostate cancer, and its fusion transcripts are present in various malignancies such as ovarian, esophageal, and prostate cancers." (PMID 37706625, 2023). "The cellular inhibitor of PP2A, CIP2A, is an oncogene who’s expression is increased in aggressive forms of prostate cancer." (PMID 29721191, 2018). "The aim of this study was to investigate the effects of CIP2A silencing on the sensitivity of PC-3 prostate cancer cells to docetaxel chemotherapy." (PMID 29399554, 2017). "ChIP-Seq data in prostate cancer cell lines from previously published studies revealed an AR binding site in CIP2A intronic region." (PMID 25965834, 2015). "AR depletion resulted in decreased CIP2A protein expression in both the AR-positive prostate cancer cell lines." (PMID 25965834, 2015). "We transfected two known AR-positive prostate cancer cell lines, LNCaP and VCaP, with siRNAs against AR and estimated the CIP2A protein levels." (PMID 25965834, 2015). "To date, CIP2A has been shown to be overexpressed in several cancers, including gastric cancer, head and neck squamous cell carcinoma, colon cancer, prostate cancer, cervical cancer, and breast cancer." (PMID 23342256, 2012). "All except for two prostate cancer specimens (96.6%) exhibited CIP2A immunopositivity in the prostate adenocarcinoma cells, but no staining was present in the stroma." (PMID 20964854, 2010). "In the present study we demonstrated an increased expression of CIP2A in the human prostate cancer epithelium as compared with BPH." (PMID 20964854, 2010).
prostate carcinoma (continued). "Further studies are required to demonstrate the prognostic role of CIP2A in prostate cancer and its value in the identification of aggressive disease forms." (PMID 20964854, 2010). "The prognostic significance of CIP2A in prostate cancer needs to be evaluated in a larger cohort with sufficient follow-up times." (PMID 20964854, 2010). "Expression of the CIP2A protein was studied using immunohistochemistry in prostate cancer (n = 59) and in benign prostatic hyperplasia (n = 20) specimens." (PMID 20964854, 2010). "Expression of CIP2A was increased in prostate cancer epithelium as compared with the benign hyperplastic epithelium (p < 0.001)." (PMID 20964854, 2010). "The authors concluded that CIP2A silencing may potentiate the antiproliferative effects of docetaxel and this might be a promising therapeutic approach in prostate cancer treatment." (PMID 37065867, 2023). "CIP2A is a cellular inhibitor of protein phosphatase 2A, a tumor suppressor in prostate cancer." (PMID 36882784, 2023). "Therefore, targeting of CIP2A can be considered as a novel strategy for targeted prostate cancer synergy therapy." (PMID 29399554, 2017). "To study the role of CIP2A in prostate cancer, we first investigated the expression and androgen regulation of this gene in clinical tissue samples, prostate cancer cell lines and different cell populations from benign prostate hypertrophy (BPH), HN-PC and CRPC patient samples." (PMID 25965834, 2015). "However, additional mouse pre-clinical studies are required to further strengthen CIP2A's role in therapy against prostate cancer." (PMID 25965834, 2015). "Likewise, in acute myeloid leukemia, prostate cancer, and other malignancies, increased CIP2A predicts poor differentiation and worse consequences." (PMID 24307892, 2013). "Importantly the effects were not cell line specific as either chemical or siRNA-based MEK1/2 inhibition inhibited CIP2A protein expression also in PC-3 prostate cancer cell line." (PMID 21445343, 2011). "In addition, ETS1 positively regulated CIP2A expression in PC-3 and LNCaP prostate cancer cell lines." (PMID 21445343, 2011). "We showed that expression of the CIP2A protein is increased in aggressive forms of prostate cancer." (PMID 20964854, 2010). "CIP2A immunostaining intensity in benign prostatic hyperplasia and prostate cancer." (PMID 20964854, 2010). "Furthermore, CIP2A auto-antibodies were present more frequently (29% vs. 16%) in the sera of prostate cancer patients with a high Gleason score (seven or higher) when compared to patients with less aggressive disease." (PMID 20964854, 2010). "The aim of this study was to investigate expression of the CIP2A protein in prostate cancer specimens and in BPH samples, and to examine whether CIP2A immunopositivity is associated with clinicopathological parameters in these patients." (PMID 20964854, 2010). "The CIP2A polymorphism alone did not influence prostate cancer risk." (PMID 36882784, 2023). "Cancerous inhibitor of protein phosphatase 2A (CIP2A) is an oncoprotein overexpressed in human malignancies, including prostate cancer (PCa)." (PMID 36098827, 2022). "We demonstrate that CIP2A is overexpressed in PC and CRPC cases and promotes the viability and clonogenicity of AR-responsive prostate cancer cells." (PMID 25965834, 2015). "The authors also confirmed that in other cell types (human gastric and prostate cancer cells), the same TFs exhibit differential results regarding CIP2A expression, since ETS1 downregulation (without ELK1 silencing) was adequate to decrease CIP2A." (PMID 40862737, 2025). "Additionally, LRRC59 has been shown to transport CIP2A (cancer inhibitor of PP2A) into the nucleus, disrupting mitotic checkpoints and deregulating the cell cycle in prostate cancer cells." (PMID 31387239, 2019).
prostate carcinoma (continued). "Since, the effect of CIP2A suppression on docetaxel induced cytotoxicity against prostate cancer cells has not been reported, this study investigated the effects of CIP2A silencing on the sensitivity of PC-3 cells to docetaxel chemotherapy." (PMID 29399554, 2017). "Based on these findings, we suggest therapeutic targeting of CIP2A, an established endogenous inhibitor of PP2A as a novel approach to simultaneous target both the luminal type mass of prostate cancer, as well as the tumor initiating capacity of the SC populations." (PMID 25965834, 2015). "Expression of CIP2A has been detected in several carcinomas, but its expression and significance in prostate cancer has not been examined so far." (PMID 20964854, 2010).